AQP5 (aquaporin 5)
Diseases named in the same sentence as AQP5 in open-access papers (continued):
Sharing a sentence is not in itself a finding about the gene and the disease.
breast carcinoma (continued). "We aimed to examine the potential role of AQP5 in the progression of human breast cancer cells." (PMID 22145049, 2011). "In conclusion, AQP5 overexpression is likely to play a role in cell growth and metastasis of human breast cancer and could be a novel target for anti-breast cancer treatment." (PMID 22145049, 2011). "Since AQP5 is highly expressed in the mammary tumor library, AQP5 may be an important marker protein involved in tumorigenesis and progression." (PMID 22145049, 2011). "Interestingly, AQP5 differently impacted ROS levels in breast cancer cell lines." (PMID 40244097, 2025). "Interestingly, AQP5 differentially impacted ROS levels in breast cancer cell lines." (PMID 40244097, 2025). "Of note, breast cancer patients with positive AQP expression (212/591 cases) showed a less favorable breast cancer specific survival rate over 7 years of follow and we further conclude that AQP5 expression is an independent molecular marker associated with worse clinical outcomes." (PMID 36706090, 2023). "AQP5 may also serve as a prognostic marker for ductal breast cancer." (PMID 30555637, 2018). "Therefore, AQP5 expression could be a novel biomarker for cell growth and metastasis of human breast cancer, and hence AQP5 might be a critical target for anti-breast cancer treatment." (PMID 22145049, 2011). "Therefore, hyperosmotic stress by 100 mM sorbitol and hence selective AQP5 downregulation could decrease the cell proliferation and migration of human breast cancer cells (ERα-positive MCF7 cells)." (PMID 22145049, 2011). "The characteristics of metastatic breast cancer cells are diverse, including EMT and increased AQP5 expression." (PMID 38774409, 2024). "AQP1, AQP3, AQP4, AQP5, AQP7, and AQP9 expression were evaluated because these AQPs are expressed in breast tumors and have begun to be characterized as having roles in breast cancer progression and metastasis." (PMID 39123442, 2024). "Transcriptomic analyses using the Human Protein Atlas database revealed higher mRNA levels of several AQPs in human breast cancer, namely AQP1, AQP3, AQP5, AQP7, AQP9 and AQP11, when compared to overall median AQP expression levels in the biopsies." (PMID 37681917, 2023). "A previous study performing transcriptomic analyses on breast cancer biopsies revealed increased mRNA expression of AQP1, AQP3, AQP5, AQP7, AQP9 and AQP11 when compared to overall median AQP levels in the biopsies." (PMID 37681917, 2023). "In human breast cancer MDA-MB-231 cells, exosome-mediated delivery of miR-1226-3p, miR-19a-3p, and miR-19b-3p targeted Aqp5 mRNA and impeded cell migration." (PMID 36768212, 2023). "Next, we outline the roles in breast cancer of AQP1, AQP3, AQP4, AQP5, and AQP7, which are the only AQPs that have begun to be characterized as having roles in breast cancer progression and as potential prognostic markers." (PMID 36212456, 2022). "The mRNA expression levels of AQP8, AQP9, and AQP10 were upregulated, while those of AQP3, AQP4, AQP5, and especially AQP7, were downregulated in breast cancer based on the Oncomine database." (PMID 36212456, 2022). "In adriamycin (ADR)-resistant breast cancer cell line MCF-7 (MCF-7/ADR), AQP5 inhibition inhibited proliferation and induced apoptosis." (PMID 36212456, 2022). "AQP3 and AQP5 were detected in human breast cancer tissues, specifically in the membrane and cytoplasm of triple negative breast cancer (TNBC) patients, with AQP5 highly expressed in the invasive front of the tumors." (PMID 36212456, 2022). "Once recognized as overexpressed in cancer, AQP3 was getting in the focus as a possible prognostic marker for triple negative breast cancer together with AQP5, as well as for HER2 positive early breast cancer." (PMID 33947079, 2021).
breast carcinoma (continued). "Additionally, overexpression of AQP5 was associated with worse outcomes in early breast cancer patients regardless of tumour type and stage, suggesting it as an independent prognostic marker of survival, particularly in hormone receptor-positive patients who underwent curative surgery." (PMID 33947079, 2021). "Other genes were associated with cell adhesion and migration of breast cancer cell [DUOXA1 and PGAM1], prognosis of breast cancer [PGK1 and KLK10], or clinical outcome in breast cancer [RBM3 and AQP5]." (PMID 34497807, 2021). "In conclusion, our findings highlight for the first time the role of PIP as a protein controlling AQP5 localization in human salivary glands but extend beyond due to the PIP-AQP5 interaction described in lung and breast cancers." (PMID 34440877, 2021). "A few studies have reported the expression of AQPs in breast cancer, mainly AQP1, AQP3, and AQP5, that were found higher expressed in tumors than in normal adjacent tissues." (PMID 31379986, 2019). "In breast cancer cells, AQP5 polarizes to the leading edge of migrating MDA-MB-231 cells, and that knockdown of AQP5 in these cells significantly suppressed cell migration velocity in narrow channels." (PMID 26912239, 2016). "A recent study of human breast cancer showed that, among the 13 AQP members, only AQP1, AQP3, and AQP5 expression is elevated in breast cancer tissues relative to normal tissues." (PMID 23468877, 2013). "Standardized mRNA levels of AQP5 (AQP5 mRNA/GAPDH mRNA) in lung and breast cancer tissue (positive control) and normal peripheral blood lymphocytes (negative control) were compared to that of CML cells for comparison." (PMID 18612408, 2008). "AQP5 is absent in normal breast tissue but is expressed in breast cancer, where it shows differential expression among subtypes, with higher expression linked to worse prognosis and metastatic spread." (PMID 40244097, 2025). "Consistent with this hypothesis, our findings demonstrate that oxidative stress differentially modulates AQP5 and NRF2 expression in breast cancer cell lines with varying degrees of malignancy." (PMID 40244097, 2025). "We utilized breast cancer cell lines representing different subtypes and degrees of malignancy—HR+ (MCF7), HER2+ (SkBr-3), and TNBC (SUM 159)—all of which exhibit low basal levels of AQP5 mRNA." (PMID 40244097, 2025). "Breast cancer cell lines overexpressing AQP5 (AQP5 cells) showed greater sensitivity to hydrogen peroxide, with a significant decrease in viability observed at 20 μM (MCF7-AQP5: p = 0.0205; SkBr-3-AQP5: p < 0.0001; SUM 159-AQP5: p = 0.0022)." (PMID 40244097, 2025). "AQP5 overexpression did not activate the PI3K/AKT signaling pathway in breast cancer cell lines, as evidenced by the lack of increase in levels of phosphorylated AKT and the pAKT/AKT ratio." (PMID 40244097, 2025). "In all three tested breast cancer cell lines, AQP5 overexpression did not activate the PI3K/AKT signaling pathway, as evidenced by the lack of an increase in phosphorylated AKT or the pAKT/AKT ratio." (PMID 40244097, 2025). "The aim of this study is to investigate the effects of prolonged oxidative stress on Aquaporin 3 (AQP3), Aquaporin 5 (AQP5), and signaling pathways in breast cancer cell lines of different malignancies alongside a non-tumorigenic breast cell line." (PMID 38929065, 2024). "Of note, among 591 patients, 7 patients were male breast cancer patients, all of which breast cancer did not have a strong AQP5 expression." (PMID 36706090, 2023). "However, in breast cancer the FOXO family is down-regulated, while AQP5 is up-regulated and positively correlated with its malignancy." (PMID 38136293, 2023). "Likewise, targeting AQP5 together with targeting HER2 for BC patients with AQP5/HER2 strongly positive group may provide a potential therapeutic opportunity, considering the accumulated success of Herceptin in managing HER 2 strong positive breast cancers." (PMID 36706090, 2023).
breast carcinoma (continued). "In invasive ductal carcinoma (IDC) patient tissues, high AQP5 expression did not correlate with Ras but positively correlated with Rac1, which makes Rac1 a candidate downstream target of AQP5 in breast cancer." (PMID 36212456, 2022). "The altered expression of a number of molecular markers, including the progesterone, estrogen, and prolactin receptors, the Na/K/2Cl cotransporter proteins (NKCC1) and aquaporin 5 (AQP5), and several markers of skin differentiation (Sprr2A and keratin 6) has been reported in breast cancer." (PMID 24338153, 2014). "Previous studies suggested that AQP1 could facilitate cell migration in 4T1 breast cancer cells, and that AQP5 is required for proliferation and migration in MCF-7 breast cancer cells." (PMID 23468877, 2013). "In the present study, sorbitol treatment suppressed the migration and proliferation of breast cancer cells, where AQP5 expression was significantly decreased, but not AQP3." (PMID 22145049, 2011). "Moreover, RT-PCR analysis revealed that AQP3 and AQP7 mRNA expression was also observed in human breast cancer MCF7 cells, in addition to AQP5 expression." (PMID 22145049, 2011). "The expression level of AQP5 in CML cells was lower than that of lung and breast cancer tissues." (PMID 18612408, 2008). "However, the relative mRNA expression level of AQP5 in CML cells is found to be lower than that of lung and breast cancer." (PMID 18612408, 2008). "In this review, we discuss the roles of AQP1, AQP3, AQP4, AQP5, and AQP7 in breast cancer progression and metastasis, including the role of AQPs in the tumor microenvironment, to highlight potential contributions of stromal-derived to epithelial-derived AQPs to breast cancer." (PMID 36212456, 2022). "Indeed, considering AQP5 and PIP have been involved in lung and breast cancers, our findings concerning AQP5-PIP protein-protein interaction may help to deepen the comprehension of the pathogenesis in various human pathologies." (PMID 34440877, 2021). "Interestingly, this study found that AQP5 was expressed mainly in cell membranes of mammary carcinomas, with AQP5 being not detectable in normal breast tissues." (PMID 24338153, 2014). "In addition, AQP1 could facilitate cell migration in 4T1 breast cancer cells, AQP5 is required for proliferation and migration in MCF-7 breast cancer cells." (PMID 23468877, 2013). "Since AQP5 is a peroxiporin, we were interested in whether overexpression of AQP5 affects the intracellular generation of ROS upon the exogenous addition of a range of H2O2 concentrations (0, 2.5, 5, 10, 20, 40, 70, and 100 μM) in the tested breast cancer cell lines." (PMID 40244097, 2025). "In breast cancer cell lines, AQP5 knockdown increased the MAPK signal transduction pathway, decreasing cell invasion and metastasis and growth while enhancing chemosensitivity, indicating that AQP5 could be advantageous as a predictive biomarker and therapeutic target." (PMID 38336645, 2024). "AQP3 and AQP5 are strongly expressed in cancer tissues and AQP3-mediated H2O2 transport has been related to breast cancer cell migration, but studies with human AQP5 are lacking." (PMID 31277235, 2019). "However, the relationships between AQP5 and NSCLC, breast cancer or colorectal adenocarcinoma have not been fully elucidated, and, therefore, further studies are needed in order to verify the role of AQP5 in vivo and its application in clinical practice." (PMID 36766810, 2023).
colorectal cancer (29 papers, 2008 to 2025). A primary or metastatic malignant neoplasm that affects the colon or rectum. "Previous studies have suggested that AQP5 expression is increased in colorectal cancer tissues and is associated with the progression and prognosis of colorectal cancer." (PMID 40760228, 2025). "Similar findings have been reported in colorectal cancer, in which AQP5 overexpression was associated with differentiation, tumor stage, and metastasis." (PMID 32075009, 2020). "High AQP5 expression correlated with an increase in phosphorylated SMAD2, promoting EMT in colorectal cancer, whereas AQP5 silencing was associated with a down-regulation of phosphorylated SMAD2, and a repressed EMT response." (PMID 29922644, 2018). "Specially, AQP1, AQP3 and AQP5 expression has been demonstrated in seven human colon and colorectal cancer cell lines, and they are associated with an early stage of colorectal cancer development." (PMID 27589719, 2016). "A recent study by the same group showed that AQP5 expression in colorectal cancer is significantly associated with lung metastasis that is possibly mediated by the activation of Ras, mitogen activated protein kinase (MAPK) and Rb signalling pathways." (PMID 19513079, 2009). "In vivo experiments confirmed that overexpression of AQP5 can promote the growth of colon cancer tumor, and overexpression of AQP5 can restore the inhibition of 5-Fu on the progression of colorectal cancer." (PMID 40760228, 2025). "Firstly, to investigate AQP5’s oncogenic role, we established stable AQP5-overexpressing cell lines using colorectal cancer models RKO and HCT116." (PMID 40760228, 2025). "Overexpression of AQP5 has a certain recovery effect on the proliferation of colorectal cancer cells inhibited by 5-Fu." (PMID 40760228, 2025). "Upregulation of AQP5 in lung adenocarcinoma and colorectal cancer has been identified, making it a prognostic biomarker." (PMID 38336645, 2024). "AQP5 is also postulated as a predictive biomarker for colorectal carcinoma, with AQP5 concentrations correlated with the number of cancerous cells in circulation and the likelihood of liver metastases." (PMID 38336645, 2024). "In human colorectal cancer cell lines, AQP5 induced the activation of phosphorylated-mothers against decapentaplegic homolog 2/3 (p-Smad2/3), which resulted in EMT." (PMID 36768212, 2023). "In colorectal cancer, AQP5 expression activated the WNT/β-catenin, predicted poor clinical outcome, increased chemoresistance to 5-fluorouracil, and promoted tumor growth." (PMID 36768212, 2023). "In human colorectal cancer cell lines, AQP5 was involved in vascular endothelial growth factor (VEGF) A expression, secretion, and concomitant angiogenesis, but the involvement of the Ras-MAPK signaling pathway remains to be assessed." (PMID 36768212, 2023). "In human colorectal cancer cell lines, Aqp5 silencing altered EMT by reducing the expression of mesenchymal cell markers (N-cadherin, Vimentin, and Snail) and increasing the expression of epithelial cell marker (E-cadherin)." (PMID 36768212, 2023). "Some studies have shown that AQP5 expression is upregulated in colon and colorectal cancer compared to normal colonic tissue, where its expression is rarely detected, improving drug resistance." (PMID 35619903, 2022). "AQP5 affects the chemosensitivity of colorectal cancer cells (CRC), where AQP5 expression is upregulated in CRCs and 5-FU-resistant cells." (PMID 36212456, 2022). "Researchers found that miR-185-3p overexpression enhanced the chemical sensitivity of drug-resistant colorectal cancer (CRC) cells through inhibiting AQP5, offering potential therapeutic targets for CRC cells that are resistant to 5-FU." (PMID 36304901, 2022). "mRNA expression of AQP1, AQP3, and AQP5 was examined in seven colon and colorectal cancer cell lines, and protein expression was confirmed in four of these cell lines." (PMID 35847914, 2022).
colorectal cancer (continued). "The expression and functions of AQP1 and AQP5 have been the main focus of papers published in the colorectal cancer field." (PMID 32679804, 2020). "For example, in colorectal cancer, the overexpression of AQP5 can promote the invasion and migration of cancer cells by activating EMT." (PMID 33343628, 2020). "AQP5 similarly has been proposed as a prognostic biomarker for colorectal cancer, with AQP5 levels found to be proportional to numbers of circulating tumors cells and risk of liver metastases." (PMID 32679804, 2020). "In studies of AQP1, AQP3 and AQP5 expression, some of these proteins were detected in colon cancer tissues and colorectal cancer cells, indicating that they play a role in colorectal cancer development." (PMID 32662230, 2020). "They affect AQP2, AQP5 and AQP8, where they are associated with nephrogenic diabetes insipidus, keratoderma and colorectal cancer, respectively." (PMID 29799470, 2018). "AQP5 is overexpressed in lung, chronic myelogenous leukemia, ovarian, stomach, pancreatic and colorectal cancers." (PMID 30555637, 2018). "AQP5 overexpression has been observed in lung adenocarcinoma and colorectal cancer; therefore, it is a prognostic biomarker." (PMID 30555637, 2018). "AQP5 was over-expressed in colorectal cancer and a strong prognostic biomarker for colorectal cancer." (PMID 25886458, 2015). "To investigate the clinical significance of AQP5 expression in colorectal carcinoma tissues, we analyzed the clinicopathological parameters of the patients." (PMID 23148732, 2012). "AQP5 was mainly expressed in colorectal carcinoma cells and barely expressed in paraneoplastic normal tissues." (PMID 23148732, 2012). "The results showed that AQP5 mRNA was abundant in colorectal carcinoma tissue but undetectable in adjacent normal colon tissue." (PMID 23148732, 2012). "Our results showed that AQP5 was mainly expressed in colorectal carcinoma cells and barely expressed in paraneoplastic normal tissues." (PMID 23148732, 2012). "Previous studies have shown an upregulation of AQP5 in ovarian tumors, colorectal carcinomas, and in human small cell lung cancer." (PMID 20806077, 2010). "Based on these preliminary findings and prior observations we had with AQP1 in NSCLC and AQP5 in colorectal cancer study, we have examined the expression profile of AQP5 in a large panel of clinical samples." (PMID 18478076, 2008). "Overexpression of AQP5 can promote the growth of colorectal cancer cells and promote the occurrence of drug resistance, which may be related to NF-κB signaling pathway." (PMID 40760228, 2025). "In summary, overexpression of AQP5 can promote the growth of colorectal cancer tumor and promote the occurrence of chemotherapy resistance, and the mechanism may be related to NF-κB signaling pathway." (PMID 40760228, 2025). "miR-185 regulates AQP3 and AQP5 expression, exerting its therapeutic effect by compromising squamous cell carcinoma and colorectal cancer progression, whereas miR-877 can suppress AQP3 in gastric cancer, promoting apoptosis and reducing cell proliferation, invasion and EMT." (PMID 39941100, 2025). "The subcutaneous tumor bearing experiment showed that AQP5-overexpressing tumors exhibited accelerated growth rates, accompanied by increased tumor diameter and elevated mouse body weight, indicating that overexpression of AQP5 can promote the growth of colorectal cancer tumors." (PMID 40760228, 2025). "Our present findings suggest that AQP5 overexpression can promote colorectal cancer cell proliferation, and the mechanism may be related to activation of the NF-κB signaling pathway." (PMID 40760228, 2025). "Therefore, future research should focus on identifying miRNAs that modulate the AQP5/NF-κB axis in colorectal cancer, with the aim of developing small RNA-based therapeutics to reverse chemotherapy resistance and improve treatment outcomes." (PMID 40760228, 2025).